ATM (ATM serine/threonine kinase)
Diseases named in the same sentence as ATM in open-access papers (continued):
Sharing a sentence is not in itself a finding about the gene and the disease.
breast cancer (continued). "Individuals heterozygous for germline ATM mutations have been reported to have an increased risk for breast cancer but the role for ATM genetic variants for breast cancer risk has remained unclear." (PMID 16914028, 2006). "We also studied the tagSNPs and haplotypes in the ATM and ERBB2 genes, in addition to two mis-sense mutations in the ATM gene (2572 T→C and 4258 C→T), in relation to the overall risk of breast cancer." (PMID 17132159, 2006). "Recently, a common ATM variant, ATMivs38 -8T>C in cis with the ATMex39 5557G>A (D1853N) variant, was suggested to associate with bilateral breast cancer among familial breast cancer patients from Northern Finland." (PMID 16914028, 2006). "While genetic factors clearly play a role in conferring breast cancer risk, the contribution of ATM gene mutations to breast cancer is still unsettled." (PMID 16622469, 2006). "We estimated the risk of death from breast cancer associated with the tagSNPs in the ATM, CHEK2 and ERBB2 genes or their haplotypes." (PMID 17132159, 2006). "Even if having functional effect on the ATM protein and possibly being pathogenic, the rarity of these variants limits any potential contribution to breast cancer susceptibility." (PMID 16914028, 2006). "In order to shed further light on the putative contribution of ATM to breast cancer risk, we performed haplotyping of the ATM locus in high-risk individuals and controls of non-Ashkenazi Jewish origin." (PMID 16622469, 2006). "As radiation exposure is associated with an increased risk of breast cancer, the function of the ATM protein makes it a good candidate for a role in breast cancer predisposition." (PMID 16914028, 2006). "A recent publication refuted this and found that ATM gene mutations that cause A-T – that is, truncating, splicing and mis-sense mutations – are breast cancer susceptibility alleles." (PMID 17132159, 2006). "Two common ATM variants, 5557G>A and ivs38-8T>C, previously suggested to associate with bilateral breast cancer, were genotyped in an extensive set of 786 familial and 884 unselected breast cancer cases as well as 708 healthy controls." (PMID 16914028, 2006). "Altogether, our results suggest very minor effect, if any, of ATM genetic variants on familial breast cancer in Southern Finland." (PMID 16914028, 2006). "Among our familial breast cancer patients screened for the whole ATM gene, both of the variants 5557G>A and ivs38-8T>C were present in altogether three haplotypes (haplotypes 8)." (PMID 16914028, 2006). "Overall, the frequency of ATM mutations found in breast cancer patients in the general population has been low, and many of the ATM variants found are too rare to be evaluated easily in case-control studies." (PMID 16914028, 2006). "The ATM gene is mutated in the rare autosomal recessive disorder ataxia-telangiectasia (A-T) and the risk of breast cancer has been found to be increased in relatives of A-T patients, in addition to A-T heterozygotes." (PMID 17132159, 2006). "Unlike the lack of a discriminating ATM haplotype among average risk Ashkenazi Jewish breast cancer women, the present study shows that ATM does contribute to familial clustering of breast cancer in non-Ashkenazim." (PMID 16622469, 2006). "ATM mutations have already been reported to increase breast cancer susceptibility, while some other sequence variants located in this gene do not seem to be linked to breast cancer." (PMID 17010193, 2006). "Only a handful of studies have used haplotyping, a mutation independent method, to assess the effect of ATM on breast cancer risk." (PMID 16622469, 2006). "Germ-line mutations in genes such as BRCA1, BRCA2, and ATM can cause a substantial increase in risk of breast cancer." (PMID 16945136, 2006). "These derived risk estimates on the potential role of ATM heterozygosity were to a large extent driven by the highly increased risk for breast cancer seen in mothers of probands." (PMID 15942625, 2005).
breast cancer (continued). "ATM (ataxia-telangiectasia mutated) heterozygous deficiency has been proposed to increase susceptibility to breast cancer." (PMID 15642165, 2005). "Assuming the existence of a true link between a mutated ATM allele and breast cancer, our data indicate that ATM heterozygosity on average infers a 2.9-fold (95% CI, 1.9–4.4) increase in the risk for female breast cancer." (PMID 15942625, 2005). "Recently, epidemiological studies on excess risk for breast cancer in ATM heterozygosity were reported." (PMID 15642165, 2005). "In this study, we investigated the prevalence of these two ATM gene mutations in a large population-based series of women with bilateral breast cancer compared with the frequency among women with unilateral breast cancer." (PMID 14562025, 2003). "Combined, these results provide evidence for an increased breast cancer risk associated with specific ATM gene mutations." (PMID 14562025, 2003). "In the present study, we focused on the frequency of the 7271T>G and IVS10-6T>G ATM gene mutations, because prior studies of multiple-case families found these two mutations to be associated with excess breast cancer." (PMID 14562025, 2003). "We screened 47 women who developed later onset, sporadic breast cancer for ataxia telangiectasia mutated (ATM) mutations." (PMID 10471049, 1999). "Sixteen HR breast cancer patients showing mainly acute reactions (and seven HR patients with other cancers) were tested for ATM mutations using the restriction endonuclease fingerprinting assay." (PMID 9413938, 1997). "Moreover, ATM PTVs show a stronger association with estrogen receptor (ER)–positive breast cancer than with ER-negative breast cancer." (PMID 41596415, 2026). "Heterozygous protein-truncating variants (PTVs) in ATM are associated with a roughly twofold increased risk of breast cancer (BC) and markedly elevated risks for other malignancies, including pancreatic cancer (~6.5-fold), gastric cancer (~3.0-fold), and prostate cancer (~2.6-fold)." (PMID 41596415, 2026). "Moreover, in an exploratory analysis of grouping genes that were previously reported to predispose toward ER-positive disease, use of E + P MHT was modestly associated with high breast cancer risk in women with ATM or CHEK2 PVs." (PMID 40298171, 2025). "Furthermore, downregulation of EME1 was also observed when SETD1A was depleted from BRCA1-mutated HCC1937 breast cancer cells, or ATM-mutated H1395 lung cancer cells, suggesting that this represents a conserved mechanism in multiple cancer types." (PMID 39994444, 2025). "The results suggested that annual MRI screening from 30 to 35 years, followed by annual mammography at 40 years, might reduce breast cancer mortality by over 50% for women with ATM, CHEK2, and PALB2 P/LP variants." (PMID 39858629, 2025). "Also, ATM c.7570G > C maintained the status of a high-risk allele (0.6% prevalence in breast cancer cases with OR 25.6), although the risk estimation is with wide CIs (3.35–196.05)." (PMID 40009290, 2025). "Increased levels of the kinase ataxia telangiectasia mutated (ATM), which mediate the HR pathway, were found in chemoresistant breast cancer cells, and cisplatin treatment was associated with increased expression of the DSB repair protein RAD51, inducing chemoresistance in breast cancer cells." (PMID 39863855, 2025). "For instance, the missense pathogenic variant c.7271T>G in ATM may considerably increase the risk of breast cancer in a similar proportion as P/LP variants in BRCA2." (PMID 39858629, 2025).
breast cancer (continued). "Recent evidence has demonstrated that specific variants of the ATM gene are associated not only with an increased risk of breast cancer development and poorer clinical outcomes, but also with similar associations observed in esophageal SCC and colorectal cancer." (PMID 41235705, 2025). "ATM loss-of-function variants are significantly associated with increased breast cancer risk." (PMID 40974429, 2025). "Therefore, more data is needed to support our findings that BRCA1/2 incidence is lower in NB, giving way to higher frequencies of variants in other breast cancer genes such as ATM." (PMID 39907309, 2025). "An association between pathogenic heterozygous ATM variants and cancer susceptibility was first noted for breast cancer (MIM #114480), when a moderately increased risk was demonstrated for carrier women, first in Ataxia-Telangiectasia families, then in the general population." (PMID 39984762, 2025). "Moreover, and in agreement with preceding data, loss of SETD1A also restored Olaparib-induced RAD51 foci formation and thus HR activity in both BRCA1-mutated ovarian and breast cancer cell lines and in ATM-mutated lung cancer cells." (PMID 39994444, 2025). "In contrast, mutations in ATM were linked to a high prevalence of Her2-positive tumors, an interesting finding considering that Her2+ tumors typically account for only 20%–30% of all breast cancers." (PMID 40259910, 2025). "PVs in BRCA1, BRCA2, CHEK2, and ATM increase the lifetime cancer risk of breast cancer." (PMID 38929805, 2024). "Furthermore, carriers of PALB2 mutation have a 35% cumulative risk of developing breast cancer at the age of 70 years, and ATM with PVs has been detected in 1.2%–6.9% of all breast cancer cases." (PMID 39590127, 2024). "Indeed, in a recent case report of a female patient carrying two heterozygous pathogenic variants in BRCA2 and ATM, breast cancer was diagnosed at 34 and pancreatic cancer at 48 years." (PMID 38929805, 2024). "ATM has been associated with a range of cancers in addition to breast cancer." (PMID 39543654, 2024). "The majority of breast cancers in carriers of ATM mutations are ER-positive." (PMID 39543654, 2024). "The present study pioneered the acquisition of the mutational landscape of the breast cancer susceptibility genes (ATM, CHEK2, PALB2, and XRCC2) using next-generation whole-exome sequencing from paraffin-fixed FFPE tissue blocks obtained from the breast cancer patients of Pashtun ethnicity." (PMID 38784039, 2024). "In our analysis of genetic mutations, HR+ patients had more ATM mutations, and a high expression level of ATM has been reported to be associated with an increased risk of pancancer, including breast cancer, and may lead to chemotherapy resistance." (PMID 38379328, 2024). "ATM mutations are associated with breast and other cancer susceptibilities and may confer a risk of contralateral breast cancer in patients undergoing radiotherapy." (PMID 38355628, 2024). "On the other hand, we showed that coupling the identification of a variant in ATM or CHEK2 with the calculation of a PRS might effectively identify women most at risk of breast cancer." (PMID 39669587, 2024).
breast cancer (continued). "A mutation in ATM: c.7969A>T was also found in the BRCA2 gene that is linked to breast carcinoma." (PMID 39281240, 2024). "ATM gene mutation carriers are predisposed to estrogen-receptor-positive breast cancer (BC)." (PMID 36640339, 2023). "The estimated lifetime risk of acquiring breast cancer with an ATM, CHEK2, PALB2 mutation is greater than 20% which is considered a “moderate risk” compared to the effects of the pathogenic variants in BRCA1 and BRCA2 genes with a lifetime risk of approximately 50%." (PMID 37239898, 2023). "This led to the definition of ATM as a breast cancer susceptibility gene with moderate penetrance." (PMID 37509701, 2023). "Heterozygous ATM pathogenic variants are known to result in significant breast cancer susceptibility and confer an increased risk for gastric, pancreatic, colorectal, ovarian, and prostate cancers (and susceptibility to breast cancer; MIM #114480)." (PMID 37509701, 2023). "Pathogenic variants detected in other breast cancer susceptibility genes, such as ATM, CHEK2, PALB2, RAD51, and BARD, may also explain a proportion of the genetic risk." (PMID 37239898, 2023). "Indeed, our study in breast cancer cells and a report on high-risk myelodysplastic syndrome and acute myeloid leukaemia confirm that targeting ATM abrogates canonical NF-κB signalling." (PMID 37835430, 2023). "The CHEK2 and ATM genes are known to be implicated in the development of breast cancer, but the exact association is not clearly understood, and insufficient data are published about the variants classified as having “unknown significance” in these genes." (PMID 37239898, 2023). "ATM is a moderately penetrant gene associated with a 20–40% risk for breast cancer." (PMID 37239058, 2023). "To date, germline RAD51D mutations have only been associated with increased risk of ovarian cancer and ATM germline mutations have primarily been shown to increased risk of breast cancer as well as case familial cases of ovarian, prostate, and pancreatic cancers." (PMID 37576901, 2023). "Furthermore, hypermethylation of the ATM gene (Ataxia Telangiectasia Mutated gene) body was associated with a threefold higher risk of developing breast cancer." (PMID 37506102, 2023). "Understanding the contribution of ATM alterations to breast cancer pathogenesis is crucial for improved risk assessment, early detection, and the development of targeted therapies for patients with ATM-related breast cancer." (PMID 38327652, 2023). "Several studies have reported breast cancer risk associated with carrying one missense pathogenic variant in ATM (c.7271T>G) to be high, setting it apart from other pathogenic variants in ATM in terms of the magnitude of associated breast cancer risk (e.g., OR 11.0 (1.42–85.7) p = 0.0019)." (PMID 35365198, 2022). "To investigate whether combined EZH2/ATM inhibition induces apoptosis in BRCA1-deficient mouse mammary tumor cells, we measured the percentage of Annexin V/propidium iodide double-positive cells by flow-cytometry." (PMID 35715861, 2022). "In particular, the authors reported that the sequence variants located in the ATM gene, having a significantly greater incidence in African women, may predict for adverse radiation responses in breast cancer patients." (PMID 36686808, 2022). "ATM mutations that cause ataxia-telangiectasia are breast cancer susceptibility alleles." (PMID 35563727, 2022). "There has been some debate on whether mono-allelic truncating ATM variants are associated with increased breast cancer risk." (PMID 35039564, 2022). "Breast cancer was recorded in one of ten participants with a P/LP ATM variant." (PMID 35441217, 2022).
breast cancer (continued). "We provide a rationalized approach of a synergistic therapy with EZH2 and ATM inhibition in BRCA1-deficient breast cancer that could guide further preclinical and clinical investigations." (PMID 35715861, 2022). "Our variant ATM:c.5763-1056G>A was detected in a heterozygous state in a breast cancer patient." (PMID 35806449, 2022). "The ability of combined EZH2/ATM inhibition to propagate DNA damage in BRCA1-deficient breast cancer could enhance the response to immuno-oncological treatment." (PMID 35715861, 2022). "Consequently, the obtained results with a high number of radiosensitive individuals can be related to the variation ATM association with higher breast cancer risk." (PMID 35054413, 2021). "Fibroblast cultures derived from a radio-sensitive (RS) breast cancer patient with grade 3 adverse reactions to radiotherapy were compared with normal control (NC) and hyper-radiosensitive ataxia-telangiectasia mutated (ATM) cells." (PMID 34164366, 2021). "However, both NC and RS are breast cancer patients, and ATM is known to predispose to a certain type of malignancies." (PMID 34164366, 2021). "The main reason for ATM deficiency in cancer cells is hypermethylation of the ATM promoter, with multiple cancer types including brain cancer, breast cancers, lung cancer, and head and neck squamous cell carcinoma exhibiting hypermethylated ATM promoter region." (PMID 34977872, 2021). "ATM (Ataxia telangiectasia mutated): Homozygous germline pathogenic variants in ATM are associated with ataxia-telangiectasia; but heterozygous variants also confer risk of breast cancer." (PMID 34439109, 2021). "The pooled prevalence of ATM variants in patients with breast cancer was 7% (95% CI: 5−8%)." (PMID 34493284, 2021). "According to these studies, there is an association between ATM variants and breast cancer risk." (PMID 34493284, 2021). "Loss of ATM protein expression was associated with poor overall survival in breast cancer, cervical cancer, and colorectal cancer, although the prognostic implications of ATM mutation are generally unknown to date." (PMID 34638295, 2021). "In addition, the heterozygote ATM variants increased the risk of breast cancer 1.31 times (95% CI: 1.05–1.64; I Square: 83.0%; PI square: 0.0001)." (PMID 33402103, 2021). "In the final step, after removing the duplicates, reviewing by title, abstract and full text and considering the inclusion and exclusion criteria, 18 studies were selected for the meta-analysis of the pooled association between ATM and the risk of breast cancer." (PMID 33402103, 2021). "Pathogenic variants in ATM are associated with increased breast cancer risk." (PMID 33917078, 2021). "Pathogenic ATM variants increase the risk for breast cancer by 2–3 times." (PMID 34680878, 2021). "Also, Epidemiologic studies have estimated that obligate heterozygous carriers of an ATM mutation have a 2–5-fold increased risk of breast cancer." (PMID 33402103, 2021). "Several studies have reported an association between breast cancer and ATM gene variants." (PMID 34493284, 2021). "This, together with the effect estimates observed in our study, suggests that ATM might have a similar burden and act as a moderate risk gene in melanoma, similar to what has been observed in breast cancer patients." (PMID 34262154, 2021). "In addition, it is reported that breast cancer patients with mutated ATM variants who undergo radiotherapy developed their second tumor sooner than the group with no treatment of radiation and no ATM mutations." (PMID 33402103, 2021). "This study reported that 6.6% of breast cancer patients in the USA had this ATM variant." (PMID 34493284, 2021). "ATM missense mutations among women diagnosed with BC before the age of 45 years could enhance the risk of contralateral breast cancer in radio-treated patients after a long latency period." (PMID 34068084, 2021).